IBSP (integrin binding sialoprotein)
Diseases named in the same sentence as IBSP in open-access papers (continued):
Sharing a sentence is not in itself a finding about the gene and the disease.
tumor (continued). "Univariate survival analysis showed that IBSP upregulation, lymph node metastasis status, and advanced tumor metastasis (TNM) were significantly correlated with poor prognosis (P < 0.05)." (PMID 31709184, 2019). "Knockdown of IBSP cells suppressed the SMAD4 induced growth of tumor cells." (PMID 39118232, 2024). "In addition, IBSP affects the tumor microenvironment and reduce the bone density of the lesion through receptors on the surface of the OC cells, thereby promoting bone metastases." (PMID 39118232, 2024). "In addition, studies have also shown that IBSP can enhance the proliferation and tumor metastasis of ESCC cells." (PMID 37647077, 2023). "IBSP was highly expressed in tumor tissue compared with normal tissue." (PMID 38006395, 2023). "We hypothesized that cooperation between exosomal miR-19a and IBSP generates the osteolytic bone microenvironment, enabling the ER+ tumor growth in the bone." (PMID 34465793, 2021). "However, upregulation of both factors together significantly promoted the tumor growth in the bone and osteoclastogenesis, indicating the cooperative roles of exosomal mIR-19a and IBSP in promoting osteolytic bone metastasis." (PMID 34465793, 2021). "Additionally, compared with adjacent non‐tumor tissues, the IBSP mRNA and protein levels also evidently increased in CRC liver metastatic recurrence tumors." (PMID 33987980, 2021). "Expression intensities of SPARC, COL1A1, COL5A1, COMP, IBSP, and THBS4 were interpreted in tumor stroma, as they were associated with ECM-related pathways, and the expression intensity of SORD was interpreted in tumor cells, as it was associated with the EMT pathway." (PMID 34503278, 2021). "Canonical markers were used to annotate different cell types: malignant cells (COL1A1, IBSP), myeloid cells (CD74, CD14), osteoclasts (CTSK, MMP9), pericytes (RGS5, ACTA2), endothelial cells (PECAM1, VWF), and tumor-infiltrating lymphocytes (CD3D, NKG7)." (PMID 40730548, 2025). "Transwell, colony formation, and CCK‐8 assays were further carried out to verify the relationship between IBSP and SMAD4 in tumor cells." (PMID 39118232, 2024). "In the tumor stroma, the IHC expression of COL5A1, COMP, and IBSP was significantly higher in the group with BM than that in the group without BM (p = 0.001 for COL5A1, p = 0.015 for COMP, and p = 0.003 for IBSP)." (PMID 34503278, 2021). "Our results show that si‐IBSP could rescue SMAD4‐induced cell metastasis, proliferation, and inhibit tumor progression, which contributes to the treatment and prognosis of patients." (PMID 39118232, 2024). "The specific upstream regulatory factor of IBSP and its implications in tumor treatment are still not clearly understood, as evidenced by limited research findings." (PMID 39118232, 2024). "We selected IBSP, whose clinical significance in CRC remains unclear, yet it has attracted wide attention in tumor research for this study." (PMID 33987980, 2021). "Intra-mammary fat pad injection of MCF7 with miR-19a and/or IBSP forced-expression did not induce any difference in tumor growth in vivo." (PMID 34465793, 2021). "Similar to MCF7, ectopic expression of both miR-19a and IBSP resulted in increased tumor burden in the bones, while discrete expression of miR-19a or IBSP alone did not affect the tumor growth." (PMID 34465793, 2021). "The results showed that IBSP expression was upregulated in 182 of 269 (67.7%) ESCC tumor tissues compared with that in the paired non-tumor tissues (62 of 269,23.0%)." (PMID 31709184, 2019). "Furthermore, IBSP was found to regulate epithelial-mesenchymal transition (EMT), which promotes tumor cell metastasis." (PMID 31709184, 2019). "Multivariate analysis showed that tumor differentiation degree, TNM stage and IBSP upregulation could be used as independent prognostic indicators for ESCC patients." (PMID 31709184, 2019).
tumor (continued). "Moreover, the results also demonstrated that IBSP could enhance the ability of ESCC cell proliferation and tumor metastasis, indicating that IBSP may be a valuable prognostic indicator in ESCC patients." (PMID 31709184, 2019). "Although few immune-related genes had a high expression in cold tumor, such as MMP8, most genes highly express in cold tumor are not so closely related to immune responses, including CGA, INHA, IBSP, and CHRNA9." (PMID 33816503, 2021).
cancer (44 papers, 2008 to 2026). A tumor composed of atypical neoplastic, often pleomorphic cells that invade other tissues. "In summary, IBSP has shown promising results as a cancer biomarker, and further research is needed to fully understand its potential clinical applications in cancer diagnosis, prognosis, and targeted therapy." (PMID 38006395, 2023). "High levels of IBSP have been found in various types of cancer, including colorectal cancer breast, esophageal squamous cell carcinoma." (PMID 38006395, 2023). "Unexpectedly, our study showed that IBSP was overexpressed in high-risk patients with BLCA, further indicating that abnormal expression of this gene is closely related to malignant tumors." (PMID 35646934, 2022). "Strikingly, ectopic expression of both miR-19a and IBSP together in MCF7 led to a significant increase in bone metastasis in the xenograft model with the intracardiac injection of cancer cells." (PMID 34465793, 2021). "Our data suggest both miR-19a and IBSP are positively related to bone metastasis of ER+ cancer cells." (PMID 34465793, 2021). "In this study, we found that CGA blocks the interaction between IBSP and OCs, inhibiting the pro-osteoclastogenesis effect of cancer-derived exosomes." (PMID 34465793, 2021). "Twelve genes were located in eight of the top-15 breakpoint regions, and six of these genes are associated with cancer (CACNA1B, IBSP, MEPE, NBEA, RELN and THSD7A)." (PMID 31249626, 2019). "Moreover, MMPs lead to cancer cell colonization in the bone marrow, through integrin αvβ3 and integrin αvβ5, which interact with osteopontin and integrin-binding sialoprotein (IBSP), respectively." (PMID 36900309, 2023). "Several studies have suggested that IBSP may serve as a potential biomarker for cancer diagnosis and prognosis." (PMID 38006395, 2023). "Therefore, we hypothesize that IBSP secreted from the bone lodging cancer cells can recruit the OC precursors to the micro-metastatic site followed by creating an OC precursor-enriched niche." (PMID 34465793, 2021). "The knockdown of IBSP decrease the phosphorylation of Fyn and β‐catenin, stabilize the binding of E‐cadherin–catenin complex, enhance the adhesion between cells mediated by E‐cadherin, reduce the free β‐catenin level in cytoplasm as well as inhibit the proliferation and invasion of cancer cells." (PMID 33987980, 2021). "When further interfering IBSP, the opposite effect will be exhibited, which inhibited EMT and rescued the formation of aggressive phenotype during cancer metastasis." (PMID 39118232, 2024). "Conversely, TREM1 and IBSP exhibited primary expression in TAM and secondary expression in cancer cells." (PMID 39574472, 2024). "According to studies, IBSP can form a trimolecular complex with integrins and MMP2, speeding up local matrix breakdown and cancer cell invasion." (PMID 35741689, 2022). "Integrin-binding sialoprotein (IBSP), another osteomimicry marker, and matrix metalloprotease 9 (MMP9), a marker of cancer cell aggressiveness expressed by osteoclasts in bone tissue, were also overexpressed in the BM primary culture." (PMID 27556456, 2016). "When comparing RM with PC, we identified key regeneration-related genes APOD and IBSP, along with several significant pathways: cAMP signaling pathway (HHIP), cytokine-cytokine receptor interaction (IL17D), pathways in cancer (HHIP, DAPK2), and biosynthesis of cofactors (RDH12, HAAO)." (PMID 39684926, 2024). "IBSP can form a three‐molecule complex with avb3 integrin as well as matrix metalloproteinase 2 (MMP2), and the complex accelerates local matrix decomposition along with cancer cell invasion." (PMID 33987980, 2021). "Importantly, the bone sialoprotein (IBSP) and osteopontin (SPP1) coding genes, which are regulated by RUNX2, play important roles in bone metastases derived from osteotropic cancers." (PMID 32204402, 2020).
head and neck tumors (1 paper, 2021). "The roles of IBSP in head and neck tumors have been studied." (PMID 34976784, 2021).
IBSP also shares sentences with these, for which no sentence is quoted: infection (9 papers); non-small cell lung carcinoma (4); bacterial infection (3); colorectal cancer (3); osteoarthritis (3); osteomyelitis (3); pancreatic cancer (3); prostate adenocarcinoma (3); adenocarcinoma (2); atherosclerosis (2); breast adenocarcinoma (2); glioblastoma (2); hepatocellular carcinoma (2); invasive ductal carcinoma (2); kidney stone (2); Obesity (2); ovarian carcinoma (2); pancreatic adenocarcinoma (2); papillary thyroid carcinoma (2); periodontitis (2); Sepsis (2); septic arthritis (2); Stillbirth (2); thyroid cancer (2); Ascites (1); astrocytic tumor (1); benign prostatic neoplasms (1); bone tumour (1); breast tumours (1); chronic pancreatitis (1).
A further 43 diseases each share a sentence with IBSP in 1 paper.